NPY (neuropeptide Y)
Diseases named in the same sentence as NPY in open-access papers (continued):
Sharing a sentence is not in itself a finding about the gene and the disease.
Hyperglycemia (18 papers, 2012 to 2025). An increased concentration of glucose in the blood. "Increased activity of NPY/AgRP neurons in the hypothalamic arcuate nucleus (ARC) is implicated in the pathogenesis of hyperglycemia in these animals, and the ARC is a key brain area for the antidiabetic action of FGF1." (PMID 35917179, 2022). "Ventricular delivery of NPY promotes insulin secretion and potentiates the insulinemic response to hyperglycemia, independently of food intake." (PMID 32405365, 2020). "In contrast, the application of ghrelin, galanin, NPY, and hyperglycemia (>2.5 mM glucose) to the brain resulted in sympathetic nerve inhibition." (PMID 30832213, 2019). "In vivo studies showed that lateral intracerebroventricular (i.c.v.)injection of glucose in mice mimics hyperglycaemia at 2 hrs after the injection, as detected by reduced NPY and increased POMC mRNA levels, which was correlated with the cessation of FI 63,64." (PMID 26081217, 2015). "In the present study we demonstrated that type-2 diabetic patients, in spite of the hyperglycemia that characterizes this pathology, show an increased NPY content in the ARC, suggesting that the diabetic brain sensed a negative metabolic state." (PMID 22808091, 2012). "However, unlike WT mice, CRF-OE mice display sex differences in the fasting hyperglycemia and hypothalamic NPY and POMC mRNA levels with females > males." (PMID 28101317, 2017). "However, the finding that [NPY] remained elevated suggests that hyperglycemia has a direct impact on adrenergic activity." (PMID 26885531, 2016). "Altered expression of neuropeptide Y and its receptors during hyperglycemia may contribute to coronary artery disease, due to decreased angiogenesis, increased apoptosis, and increased vascular smooth muscle proliferation." (PMID 24000330, 2013). "Because metformin and insulin have an inhibitory effect on appetite and hyperglycemia, we wanted to determine if T2DM subjects had different levels of NPY expression based on their treatment." (PMID 32814716, 2020). "Interestingly, exposure to maternal hyperglycemia only during lactation (i.e., through maternal milk) was sufficient to decrease both POMC and α‐MSH neurons in the ARC, with no changes in NPY neuronal number." (PMID 40474775, 2025).
Cognitive impairment (17 papers, 2013 to 2025). Abnormal cognition is characterized by deficits in thinking, reasoning, or remembering. "High-dose, broad-spectrum antibiotic administration in mice (designed to mimic germ-free states) caused cognitive deficits, altered gut microbial profiles, and modulated cognition-related signaling molecules like neuropeptide Y, serotonin transporter, and NA subunit." (PMID 35320274, 2022). "Changes in interneuron numbers have been widely implicated in a number of cognitive deficits, therefore we quantified cortical interneuron populations including parvalbumin (PV+), calretinin (CR+), and neuropeptide Y (NPY+) interneurons in EfnB1Y/+ and EfnB1Y/− mutants." (PMID 24520368, 2014). "Therefore, we hypothesized that withdrawal of nicotinic cholinergic input to NPY neurogliaform cells is a key component of the pathological mechanism underlying presbycusis with tinnitus and cognitive impairment, solely based on animal models." (PMID 29681847, 2018). "Research has shown strong associations between the structure of the gut microbial community and NPY expression, as well as cognitive impairments mediated by the microbiota–gut–brain axis." (PMID 41462683, 2025). "In an animal experiment, the Y1 receptor was shown to play an important role in AD-related cognitive impairment, as memory impairment in rats was improved by the NPY and Y1 receptor agonist, while the Y1 receptor antagonist had the opposite effect." (PMID 39585059, 2024). "High levels of NPY in the cerebrospinal fluid have been reported to be related to cognitive impairment in patients with subarachnoid hemorrhage." (PMID 34917635, 2021). "The aim of this study was to decipher the concentrations of SOM and NPY in elderly subjects with cognitive impairment and analyze these relationships with the other AD biomarkers." (PMID 30327597, 2018). "The aim of this study was to analyze CSF SOM, NPY and CSF Aβ1–42; T-Tau, P-Tau relationships in 43 elderly mild cognitively impairment (MCI) participants from the Biomarker of AmyLoïd pepTide and AlZheimer’s disease Risk (BALTAZAR) cohort." (PMID 30327597, 2018). "The authors concluded that circulating metabolites and the cerebral neuropeptide Y system play an important role in the cognitive impairment and dysregulation of cerebral signaling molecules due to antibiotic-induced gut alterations." (PMID 28966571, 2017). "Thus, the sprouting of NPY fibers observed in the aged Tg2576 mice likely enhanced granule cell inhibition, which in turn may have been responsible for the cognitive impairment in these mice." (PMID 39585059, 2024). "Therefore, the sprouting of NPY fibers observed in aged Tg2576 mice is likely to enhance granule cells inhibition, which in turn, may participate to cognitive deficits in these mice." (PMID 24086745, 2013). "Previous studies suggested that GBE alleviates cognitive impairment in epileptic animals by increasing BDNF, neuropeptide Y or increasing the differentiation of neural stem cells." (PMID 36419341, 2023). "Conversely, the downregulation of genes like NPY, CSPG5, VGF, ADAMTS2 and GPC2 among others, in astrocytes and other cell-types points to impaired neuroprotective mechanisms and compromised synaptic function contributing to cognitive deficits." (PMID 41282152, 2025). "To date, the relationships between CSF Aβ1–42, T-Tau, P-Tau and CSF SOM and NPY concentrations have never been reported especially in subjects suffering from cognitive impairment." (PMID 30327597, 2018). "In addition, a low level of CSF SOM correlates with cognitive deficits in AD while CSF NPY concentrations changes are not as well documented." (PMID 30327597, 2018).
asthma (16 papers, 2014 to 2025). "There is evidence that patients with the NPY-399C/T polymorphism and obesity have a higher probability of suffering from asthma." (PMID 34055794, 2021). "NPY has been implicated in a wide variety of autoimmune and inflammatory diseases, including asthma and COPD." (PMID 30081920, 2018). "However, another study revealed that overweight is related to a 2.5-fold increased risk of asthma in patients with particular alleles in their NPY genotype." (PMID 38542187, 2024). "Interestingly, the loss of FOXP1 and FOXP4 in the epithelium of patients with a non-Th2 asthma phenotype induces ectopic NPY production and other proteins associated with airway remodeling, such as MUC5AC." (PMID 34055794, 2021). "For example, NPY has been associated with stress-induced exacerbation in asthma." (PMID 30081920, 2018). "NPY may be elevated in asthma, which does carry a greater risk of respiratory infection." (PMID 34684394, 2021). "In an experimental model of bronchial hyperreactivity and inflammation, NPY is important for the accumulation of CD11c+ antigen-presenting cells in the airways and the activation of the Th2 immune response." (PMID 40076857, 2025). "As we found to be the case in our OVA- and HDM-challenged mice, other studies showed elevated NPY levels in various rodent models of lung inflammation as well as in the plasma of elderly asthma patients." (PMID 39345572, 2024). "Their impact on asthma symptoms can be either soothing, as for neurotensin, or aggravating, as for neuropeptide Y." (PMID 34948451, 2021). "The numerous small molecules that have been developed to either potentiate or inhibit NPY receptor offer promise for investigating NPY signaling in asthma." (PMID 30081920, 2018). "NPY is emerging as regulator of inflammation, involved in autoimmunity, asthma, cancer and many gastrointestinal disorders, such as melabsorption, short gut, inflammatory bowel disease and pancreatitis." (PMID 26606050, 2015). "We then tested whether these changes were specific to OVA-induced airway inflammation model and found a similar rise in BALF NPY in the house dust mite (HDM) model of asthma." (PMID 39345572, 2024). "NPY is present in the respiratory tract, in the nerves that innervate the smooth muscle of the bronchi, glands, submucosa, and vasculature of the airways, pointing to its significant contribution to the pathophysiology of asthma." (PMID 38542187, 2024). "Sympathetic neurons and APCs produce NPY in the airways during asthma." (PMID 39345572, 2024). "It is hypothesized that the asthma attack itself leads to excessive production of catecholamines and Neuropeptide Y, and it may trigger apical cardio-depression precipitating TCM." (PMID 36183036, 2022). "As T2Rs are also expressed in bronchial cilia, impairment of T2R function by NPY in asthma may also contribute to innate immune dysfunction in this disease." (PMID 34684394, 2021). "Although the NPY modulation has been explored in obesity, alcoholism, anxiety, depression, epilepsy and pain, its potential benefit in asthma is largely unknown and unexplored." (PMID 30081920, 2018). "In addition, in asthma patients with a high BMI, NPY level was positively correlated with adiponectin and TNF-α." (PMID 28128231, 2017). "Moreover, elevated serum levels of NPY were detected in patients with asthma and systemic lupus erythematosus suggesting its role in acute inflammatory diseases." (PMID 25221996, 2014). "Furthermore, the serum concentration of NPY is elevated during asthma exacerbation, and in the group of elderly asthmatic patients, the level of NPY was significantly higher both in the stable resting state and in acute severe condition compared to control subjects." (PMID 38542187, 2024). "Thus, elevated NPY in CRS or asthma may impact cilia function, perhaps contributing to susceptibility to infection by reducing mucociliary clearance." (PMID 34684394, 2021).
asthma (continued). "An implication therefore was that NPY might contribute to diseases like COPD and asthma, in which elevated interleukin 6 has been found in the sputum." (PMID 30081920, 2018). "However, other authors reported that NPY concentration was not markedly different between children with and without asthma or was even lower in young adult asthmatics compared to healthy controls." (PMID 38542187, 2024).
Hyperinsulinemia (16 papers, 2010 to 2025). An increased concentration of insulin in the blood. "In chow-fed WT mice, BIIE0246 increased weight gain, and caused hypercholesterolemia, hyperinsulinemia, and hepatic triglyceride and cholesterol accumulation, which actually resemble the metabolic phenotype of genetically obese NPY mice." (PMID 29674968, 2018). "In mice, a triple knockout of NPY1R, NPY2R and NPY4R prevents the hyperinsulinemia associated with NPY overexpression, indicating that NPY signalling through the NPY receptors modulates insulin secretion." (PMID 26138755, 2015). "Concurrently, hyperinsulinemia activates AgRP neurons and increases the expression of neuropeptide Y (NPY) and GABA, which synergistically upregulate hypothalamic kisspeptin and GnRH expression, further aggravating LH hypersecretion." (PMID 41239503, 2025). "Therefore, lipid-lowering and NPY down-regulation pharmacological interventions might reduce the risk of hyperlipidemia-induced serum hormonal complications such as testosterone decline, hyperinsulinemia, and increased cortisol levels." (PMID 38645495, 2024).
temporal lobe epilepsy (16 papers, 2013 to 2026). A localization-related (focal) form of epilepsy characterized by recurrent seizures that arise from foci within the temporal lobe, most commonly from its mesial aspect. "Gene therapy to treat pharmacoresistant temporal lobe epilepsy in humans is now being developed using an AAV vector (CG01) that encodes the combination of neuropeptide Y and its antiepileptic receptor Y2." (PMID 33343295, 2020). "The overexpression of NPY in the rat hippocampus resulted in a decrease in seizure frequency, and the use of the rAAV1/2-NPY vector successfully suppressed seizures in models of temporal lobe epilepsy." (PMID 39596149, 2024). "The vector also demonstrated transgene-induced decrease of glutamate release from excitatory neuron terminals and significantly increased both NPY and Y2 expression in resected human hippocampal tissue from patients with drug-resistant temporal lobe epilepsy." (PMID 37029201, 2023). "Neuropeptide Y (NPY) inhibits seizure-like activity on resected hippocampal tissues in patients treated for drug-resistant temporal lobe epilepsy." (PMID 36338344, 2022). "Our groups have explored the effects of unilateral NPY/Y2 gene therapy and shown that hippocampal overexpression of both transgenes induces significant seizure-suppressant effect in a chronic rat temporal lobe epilepsy model." (PMID 33343295, 2020). "Earlier rodent studies reported that chronic spontaneous seizures are reduced by NPY in a temporal lobe epilepsy model of rats and that high levels of brain NPY are crucial for memory and learning." (PMID 31708779, 2019). "Earlier study has reported that chronic spontaneous seizures are reduced by NPY in a temporal lobe epilepsy model of rats." (PMID 31708779, 2019). "It is reported that NPY gene therapy decreases chronic spontaneous seizures in a rat model of temporal lobe epilepsy." (PMID 28824436, 2017). "A study done in humans with temporal lobe epilepsy found similar degrees of loss of SOM- and NPY-positive dentate interneurons." (PMID 27092056, 2016). "It is known that the NPY system undergoes profound changes during many neurodegenerative diseases, as well as in experimental models of temporal lobe epilepsy, including the TMT-induced model of hippocampal injury." (PMID 26594149, 2015). "NPY immunoreactivity and Y2 receptor binding is increased in the hippocampus in patients with temporal lobe epilepsy and NPY expression is increased in the rodent brain after recurrent seizures induced chemically or electrically." (PMID 24039965, 2013). "NPY expression is increased both in rodent and human hippocampal sections from temporal lobe epilepsy (TLE) surgical samples, despite the strong loss of hilar GABAergic interneurons that physiologically express NPY." (PMID 33551745, 2020). "Currently, gene therapy is being developed for pharmacoresistant temporal lobe epilepsy using unilateral intrahippocampal gene therapy with CG01, an AAV vector mediating overexpression of NPY and Y2." (PMID 33343295, 2020).
alcohol dependence (14 papers, 2013 to 2023). Physical and psychological dependence on alcohol. "The present study aims to evaluate the association between NPY gene rs16139 variant and alcohol dependence." (PMID 34777047, 2021). "Further, the link between the NPY rs16139 polymorphism and the risk of alcoholism has been studied in many populations." (PMID 34777047, 2021). "For the precise results, further studies with large-scale animal and human models are needed to increase our understanding of the relationship between NPY variants in alcoholism." (PMID 34777047, 2021). "The association between NPY gene variant and alcoholism has been demonstrated in large cohorts of alcohol users and veterans." (PMID 34777047, 2021). "In order to find the association between NPY rs16139 variant and the risk of alcoholism, 11 studies were included in the pooled analysis." (PMID 34777047, 2021). "Other NPY gene polymorphisms have been associated with alcohol dependence including a polymorphism at the 602 position in the 5′ region and a C to T substitution at the 5671 position." (PMID 28824541, 2017). "Whereas, the ECS is also associated with emotionality, neuropeptides such as CRF and NPY are clearly involved in alcohol-related behaviors and binge alcohol drinking." (PMID 28223925, 2017). "In conclusion, there was an interaction between NPY rs16147:T>C and alcohol dependence indicating that rs16147:T>C might correlate with susceptibility for depressive symptoms among male adults with alcohol dependence during the period of ADW." (PMID 36245887, 2022). "However, in the present study, we conducted a meta-analysis to evaluate the strength of association between NPY rs16139 variant and the risk of alcoholism." (PMID 34777047, 2021). "However, further studies are needed to increase our understanding of the relationship between NPY variants in alcoholism." (PMID 34777047, 2021). "Reduction of alcohol intake following NPY infusion in predisposed animals might relate to its anxiolytic effect, since alcohol dependence is accompanied by an increased sensitivity to stress." (PMID 28824541, 2017). "Alcohol dependence withdrawal can be regarded as an acute stressor, and NPY is conducive to coping with stress-related psychological disorders." (PMID 36245887, 2022). "In contrast, the anti-stress neuropeptide NPY is decreased in the CeA in alcohol dependence, and intra-CeA infusion of NPY suppresses alcohol drinking specifically in dependent rats." (PMID 30990816, 2019). "Further support for an involvement of NPY and its receptors in the behavioral consequences of alcohol dependence come from animals with a history of alcohol dependence induced via alcohol vapor exposure." (PMID 28824541, 2017). "In an early study of the genetics of alcohol dependence, linkage analysis on the F2 intercross progenies of P and non-preferring rats revealed a chromosomal region containing a NPY precursor gene." (PMID 28824541, 2017). "Accumulating evidence points to a key role of NPY in the modulation of the development of alcohol dependence." (PMID 28824541, 2017). "In addition, a Leu7Pro polymorphism in the signal peptide region of the NPY (neuropeptide Y) gene has been found to show higher plasma NPY levels in response to physiological stress and is associated with a greater risk of developing alcohol dependence in patients." (PMID 24386135, 2013). "Furthermore, the interaction between NPY rs16147:T>C and alcohol dependence was significant (β = −0.29, p < 0.05)." (PMID 36245887, 2022). "Despite considering some limitations, Accumulating evidence of the NPY system may offer an attractive target for developing novel therapies for alcohol dependence." (PMID 34777047, 2021). "Studies that analyzed the association between NPY rs16139 and alcoholism risk did not demonstrate conclusive evidence for this relationship." (PMID 34777047, 2021).